SYS1 (SYS1 golgi trafficking protein)
Description:
Involved in protein trafficking. May serve as a receptor for ARFRP1.
Synonyms: C20orf169; dJ453C12.4; dJ453C12.4.1
Tractability: Antibody: UniProt predicts a signal peptide or a membrane-spanning region. PROTAC: ubiquitination databases record sites on it; its protein half-life has been measured.
Gene: Protein-coding gene on chromosome 20 (45,359,977 to 45,376,798, forward strand). Ensembl gene ENSG00000204070.
Subcellular location: Golgi apparatus membrane
Pathways (Reactome):
Vesicle-mediated transport: Retrograde transport at the Trans-Golgi-Network
Gene Ontology:
Molecular function: protein binding
Biological process: Golgi to endosome transport; Golgi to plasma membrane protein transport; protein localization to Golgi apparatus
Cellular component: Golgi membrane; trans-Golgi network; trans-Golgi network membrane; cytosol
Genetic constraint (gnomAD): Loss-of-function variants: 8 observed, 14.81 expected, observed/expected ratio (o/e) 0.54, 90% interval 0.32 to 0.98. The upper end of that interval is the gene's LOEUF score, 0.98, which puts it in group 4 of 6, group 1 being the genes least tolerant of losing a copy. Missense variants: 161 observed, 199.63 expected, observed/expected ratio (o/e) 0.81, 90% interval 0.71 to 0.92. Synonymous variants: 95 observed, 89.04 expected, observed/expected ratio (o/e) 1.07, 90% interval 0.9 to 1.26.
Homologues: Orthologues: dog SYS1 (100% identical), macaque SYS1 (100% identical), chimpanzee SYS1 (99% identical), guinea pig SYS1 (99% identical), rabbit SYS1 (99% identical), mouse Sys1 (97% identical), pig SYS1 (97% identical), rat Sys1 (97% identical), tropical clawed frog sys1 (77% identical), zebrafish sys1 (74% identical), Drosophila melanogaster Sys1 (43% identical), Caenorhabditis elegans T03F1.12 (35% identical). Paralogues in human: TMEM244 (17% identical).
Diseases named in the same sentence as SYS1 in open-access papers:
SYS1 is named in the same sentence as 6 diseases in open-access papers, as found by Europe PMC text mining. Sharing a sentence is not in itself a finding about the gene and the disease. The quoted sentences say what the papers report.
lipodystrophy (1 paper, 2017). A congenital or acquired disorder characterized by abnormal loss or redistribution of the adipose tissue in the body. "SYS1 targets ARFRP1 (ADP-ribosylation factor-related protein 1) and forms a complex in the Golgi membrane; deletion of Arfrp1 in mouse adipocytes led to lipodystrophy caused by failure in lipid droplet formation." (PMID 29084231, 2017).
psoriasis (1 paper, 2011). An autoimmune condition characterized by red, well-delineated plaques with silvery scales that are usually on the extensor surfaces and scalp. "The rs2245717 SNP, predicted to create an MRE for miR-155 in the SYS1 transcript, is in perfect LD with rs1008953 a SNP associating with psoriasis." (PMID 21995669, 2011).
viral infections (1 paper, 2022). "Additional host factors that were significantly enriched include those described for other viral infections, such as negative-stranded RNA virus vesicular stomatitis virus (VSV) (ARFRP1, SYS1, and YKT6) and the human immunodeficiency virus (HIV) (SRP14, DYRK1A, and IL2RA) (33, –, 37)." (PMID 35502904, 2022).
cancer (2 papers, 2024 to 2025). A tumor composed of atypical neoplastic, often pleomorphic cells that invade other tissues. "It would therefore be of interest to investigate whether the SYS1-ARFRP1-ARL5-ARMH3-PI4KB axis contributes to both viral replication and GOLPH3-driven tumorigenesis, potentially offering additional targets for anti-viral and anti-cancer interventions." (PMID 39580461, 2024).
SYS1 also shares sentences with these, for which no sentence is quoted: infection (1 paper); tumour (1).